NF2 (NF2, moesin-ezrin-radixin like (MERLIN) tumor suppressor)
Diseases named in the same sentence as NF2 in open-access papers (continued):
Sharing a sentence is not in itself a finding about the gene and the disease.
meningioma (continued). "Clinicopathologic studies have shown no definite evidence of association between high-grade gliomas and NF2, though these lesions may arise secondarily in NF2 patients, often in those who receive radiation therapy for other syndrome-associated masses such as meningiomas." (PMID 31161239, 2020). "In addition to the established association of meningioma with pathogenic aberrations in the tumour suppressor gene NF2, genomic analyses have identified genes including TRAF7, KLF4, AKT1, SMO, PIK3CA and POLR2A to possess recurrent mutations in low grade non-NF2 mutant meningioma." (PMID 33167358, 2020). "Mutations in the neurofibromin 2 (NF2) gene were among the first genetic alterations implicated in meningioma tumorigenesis, based on analysis of neurofibromatosis type 2 (NF2) patients who not only develop vestibular schwannomas but later have a high incidence of meningiomas." (PMID 31652973, 2019). "Moreover, inactivating NF2 mutations can be found in up to 60% of the tumors, supporting the classical two-hit hypothesis in meningioma pathogenesis." (PMID 31470906, 2019). "While our cohort was focused on skull base meningioma’s, investigation of sequencing data in our cohort has identified a number of non-NF2 mutations in skull base meningioma’s, This highlights a range of mutations outside the known cancer driver NF2 that may be linked to meningioma prognosis." (PMID 31565188, 2019). "For instance, NF2, an upstream regulator of the Hippo pathway, is an extensively studied tumor suppressor, and a high frequency of NF2-inactivating mutations is a characteristic of several human cancers, including acoustic neuromas, meningiomas, schwannomas, and mesothelioma." (PMID 31100975, 2019). "While NF2 mutation-driven meningiomas have been shown to differ from non-NF2 mutation-driven meningiomas with regard to histological subtype and intracranial location, the phenotypic and oncological features of meningiomas driven by NF2 mutation status remain inadequately described." (PMID 31191822, 2019). "These suggest that low PR expression and NF2 inactivation might have an important role in progesterone-associated meningioma tumorigenesis and therefore may be a potential clinical marker for females at higher risk of meningioma." (PMID 30687635, 2018). "Low expression of PR and NF2 were associated with higher risk of meningioma, suggesting that low PR expression and inactivation of NF2 might play a key role in progesterone-associated meningioma tumorigenesis and may be potential clinical marker for females at higher risk of meningioma." (PMID 30687635, 2018). "Meningiomas represent one of the first tumors to be associated with a genomic driver with the discovery that Neurofibromatosis 2 (NF2), an inherited genetic disorder characterized by the development of schwannomas and meningiomas, arose in the setting of mutations of the NF2 gene." (PMID 28923059, 2017). "However, in non-NF2 meningioma, somatic mutations in TRAF7, KLF4, AKT1 and SMO genes were reported." (PMID 26950155, 2016). "Although NF2 is the most frequently altered gene in chromosome 22, the frequency of deletions at this chromosomal region exceeds by far that of NF2 mutations in meningioma, suggesting that other genes encoded at chromosome 22 may also be involved in meningioma tumorigenesis." (PMID 25965831, 2015). "Additionally, up to 60% of these meningiomas carry inactivating mutations in the remainder NF2 allele, consistent with the classical two-hit hypothesis of tumor suppressor gene inactivation." (PMID 25965831, 2015). "Employing patient-derived NF2-deficient meningioma cells and NF2 knockdown (shRNA) human arachnoidal cells, the cell of origin for meningiomas, we established that mammalian/mechanistic target of rapamycin complex 1 (mTORC1) is negatively regulated by merlin/NF2." (PMID 26219339, 2015).
meningioma (continued). "Because group I p21-activated kinases (Paks) bind to and are inhibited by the NF2-encoded protein Merlin, we assessed the signaling and anti-tumor effects of three group-I specific Pak inhibitors - Frax597, 716 and 1036 - in NF2−/− meningiomas in vitro and in an orthotopic mouse model." (PMID 25596744, 2015). "Though there is overlap in the types of NF2 mutations/aberrations between NF2-related conditions, nonsense mutations are more frequent in neurofibromatosis 2, frameshift mutations in sporadic schwannomas, meningiomas, and ependymomas, and missense mutations in cancer." (PMID 24393766, 2014). "Subsequently, NF2 gene (located at 22q12.2) inactivation was found to be due to several mechanisms, such as mutations or allelic loss due to monosomy or deletion of chromosome 22, accounting for up to 66% in schwannomas and 18–50% in sporadic meningiomas, depending on the histopathological subtypes." (PMID 25333347, 2014). "Interestingly, an association between NF2 gene mutations and specific subtypes of meningiomas such as fibroblastic and transitional tumors has been observed, although such data could not be always confirmed in other series." (PMID 24171707, 2013). "Notably, the risk for developing meningioma, a tumor that frequently harbors Nf2 mutations, is significantly increased in patients with a history of head trauma, suggesting that such synergy may also be relevant to human tumorigenesis." (PMID 22886419, 2012). "However, recent studies show that loss of 22q12 (NF2 gene) and loss of heterozygosity have been found in pure MA and MA associated with meningioma, suggesting that MA may be neoplastic in nature." (PMID 23198201, 2012). "Abemaciclib warrants further investigation for patients with progressive grade 2 or 3 meningiomas harboring NF2 or CDK pathway alterations." (PMID 41545592, 2026). "While NF2 alterations are the most common drivers of meningioma pathogenesis, the mechanisms regulating NF2 transcription in NF2-intact tumors are poorly understood." (PMID 41642951, 2026). "Loss of NF2 and CDKN2A/CDKN2B is common in higher-grade meningiomas and promotes progression in preclinical models." (PMID 41545592, 2026). "In this study, we describe generation of the telomerase-immortalized AG-NF2-Men cell line from a grade-1 meningioma of a patient with NF2-related schwannomatosis (NF2-SWN)." (PMID 41417846, 2026). "YAP1-fusion–positive, NF2-wild-type meningiomas represent a unique pediatric subset with biology that differs from the NF2-driven tumors more commonly observed in older children and adults." (PMID 41526775, 2026). "Here, we demonstrate that KMT2C expression is markedly reduced in high-grade meningiomas and that loss of KMT2C promotes proliferation and invasion in NF2-wild-type meningioma cells." (PMID 41642951, 2026). "Tumor recurrence occurred in one patient (6.3%) with a WHO Grade II (atypical) meningioma and a diagnosis of NF2." (PMID 41526775, 2026). "As such, although there are similarities between NF2-SWN and sporadic tumours, the present study is limited by the predominant use of sporadic samples due to the lack of publicly available datasets containing both NF2-SWN VS and NF2-SWN meningioma." (PMID 41437121, 2025). "Anterior parasagittal meningiomas are often driven by TRAF7, KLF4, or SMO mutations, while posterior ones are typically NF2-driven." (PMID 40569492, 2025). "The A071401 trial additionally supports long-term twice-daily dosing and a favorable therapeutic index in NF2-mutant meningioma." (PMID 41487565, 2025). "Brigatinib shows a positive response on meningeal cells and meningiomas in NF2 patients and should be considered mainly in NF2 patients with severe, progressive, symptomatic, and inoperable meningiomatosis at an early stage." (PMID 40820211, 2025). "This deletion helps distinguish the more aggressive NF2 mutant meningiomas from their benign counterparts." (PMID 40936721, 2025).
meningioma (continued). "Second, numerous studies have demonstrated that Merlin/NF2-intact meningiomas have the most favorable prognosis and are well-suited to existing therapeutics." (PMID 40867323, 2025). "This mini review examines the contrasting roles of FAK in GBM and NF2-mutant meningiomas to underscore the importance of biological context in therapeutic decisions." (PMID 41487565, 2025). "We propose that NF2-mutant meningiomas represent a model for context-specific, synthetic lethal targeting, exemplifying a functional oncogenomics approach to precision oncology." (PMID 41487565, 2025). "The most well-characterized genomic change is biallelic inactivation of the 22q NF2 gene in nearly half of all tumors, with a high frequency in convexity meningiomas." (PMID 40867323, 2025). "The presence of NF2 alterations can be present across meningioma of all grades (Grade 1= 37%, Grade 2 = 60%, and Grade 3 = 69%) and show genomic instability." (PMID 40149634, 2025). "In our study, we analysed the most common driver mutations (NF2, AKT1, KLF4, and TRAF7) in meningioma by genomics describing co-occurrences and new mutations." (PMID 40562609, 2025). "In contrast, neurofibromatosis type 2 (NF2)-mutant meningiomas present a biologically grounded vulnerability, in which loss of the tumor suppressor moesin-ezrin-radixin-like protein (merlin) creates a synthetic lethal dependency on FAK." (PMID 41487565, 2025). "Overall, our data show low-grade meningiomas, especially those with NF2 genotype or MC ben-1, exhibit higher TAM infiltration, characterised by more microglia and fewer macrophages." (PMID 40420192, 2025). "In meningiomas, in addition to histopathological features, alterations in NF2, AKT1, TRAF7, SMO, PIK3CA, KLF4, and SMARCE1 genes are recognised as key biomarkers in molecular classification." (PMID 41009755, 2025). "For example, meningiomas exhibited two distinct clusters based on NF2 expression, and the corresponding MEN-Os maintained these differential expression levels." (PMID 39941893, 2025). "Our literature review identified 2 out of 70 patients diagnosed with NF2 who had acute seizure activity as an initial presenting symptom of their meningioma." (PMID 40637916, 2025). "We aimed to describe the immunohistochemical expression of merlin in a large series of meningiomas and relate these findings to clinicopathological features and NF2 status." (PMID 40447281, 2025). "FAK inhibition in NF2-mutant meningiomas represents a rare example of context-defined vulnerability in brain tumors." (PMID 41487565, 2025). "The repositioning of FAK inhibitors in NF2-mutant meningiomas exemplifies the potential of context-matched therapy; however, key mechanistic questions remain." (PMID 41487565, 2025). "A 60-year-old man presented with dizziness and was found to have meningioma and vestibular schwannoma, consistent with NF2." (PMID 40713130, 2025). "In case of meningiomas, chromosome 22 deletion consistently disables at least two tumor suppressor genes, one of which is NF2 and the other is yet to be determined." (PMID 40720480, 2025). "NF2-mutant meningiomas, once neglected, serve as a prototype for context-informed therapeutic development." (PMID 41487565, 2025). "In this study, we used the IOMM-Lee and CH157-MN two meningioma cell lines, which have different NF2 gene expression." (PMID 39894505, 2025). "Our literature review found that only 2 (2.9%) out of 70 patients diagnosed with NF2 had acute seizure activity as initial presenting symptoms of their meningiomas." (PMID 40637916, 2025). "Among NF2-driven meningiomas, NSB-POST-M tumors maintained the lowest Vi, suggesting that anatomical influence on aggressive growth patterns is preserved in this molecular subtype." (PMID 40569492, 2025).
meningioma (continued). "The cytological examination on thoracentesis diagnosed an epithelioid PM that followed a mild course, giving an overall survival of about one year; then the patient died because of rapidly increasing meningiomas related to NF2-SWN." (PMID 40725095, 2025). "We noted a case of a pediatric NF2 patient with three separate meningiomas of unique grades, each in disparate locations, indicating the complex interplay between various molecular and genetic features." (PMID 40637916, 2025). "NF2 mutant meningiomas typically occur along the convexity, while smoothened (SMO) mutated meningiomas are located within the olfactory groove." (PMID 40149634, 2025). "The proliferation of the NF2-wildtype meningioma cell line IOMM-Lee was enhanced by lead treatment in a dose-dependent manner within a certain range." (PMID 39894505, 2025). "NF2 patients can also present with multiple spinal tumors, including schwannomas, meningiomas, and ependymomas, all of which can be diagnosed using MRI." (PMID 40821302, 2025). "Initial results show radiotherapy enhances PFS in immunogenic and NF2-wt meningiomas, with moderate effects for hypermetabolic types and minimal benefits for proliferative cases." (PMID 39779595, 2025). "The first study was performed over an 11 year period in the Helsinki area in Finland finding that 3% of people with schwannoma and 1% of those that had meningioma had NF2-SWN." (PMID 41160189, 2025). "Copy number variations (CNVs), including losses on 1p, 6p/q, 10q, 14q, 18p/q, and gains on 2p/q, 3p, 4p/q, 7p/q, 8p/q, 13p/q, are documented especially in high‐grade NF2‐altered meningioma." (PMID 40815185, 2025). "NF2 meningiomas exhibited greater immune cell infiltration, particularly in total TAMs, M2-like TAMs, microglia, and M2-like microglia." (PMID 40420192, 2025). "Meningioma metastasis remains exceedingly rare, but risk increases with higher grade, recurrence, and molecular alterations such as BAP1 loss or NF2 inactivation." (PMID 41552249, 2025). "Alterations in NF2 are reported in more than half of meningiomas, suggesting an essential role of this gene for meningioma development." (PMID 40447281, 2025). "TRAF7 (along with NF2 and PI3K) associated meningiomas are more aggressive and recur at a significantly higher rate than other molecular subgroups of meningiomas (KLF4, POLR2A, and SMARCB1)." (PMID 41372821, 2025). "In stark contrast, meningiomas categorized into the NF2 wildtype and immunogenic molecular groups appear to benefit from adjuvant radiation therapy." (PMID 40149634, 2025). "NF2 alterations are characteristic of schwannomas and meningiomas and appear to occur much more rarely in other cancers." (PMID 40862839, 2025). "NF2 is an autosomal dominant genetic illness, characterized by bilateral tumors and additional meningiomas in the surrounding brain and spine." (PMID 41278265, 2025). "Both also expressed PTGDS, and thus cannot be distinguished based on findings in mice, where meningioma can be generated by expression of NF2 in PTGDS-expressing primordial meningeal cells." (PMID 40672210, 2025). "Overall, the current study elucidates the potential mechanism by which lead exposure promotes the proliferation of meningioma with NF2 expression for the first time." (PMID 39894505, 2025). "Furthermore, studies on skin tumors, vestibular schwannomas, and meningiomas in NF2-SWN patients have suggested that loss of heterozygosity due to NF2 allele deletion and the inactivation of NF2 gene transcription through hypermethylation may represent additional mechanisms of tumorigenesis." (PMID 41209567, 2025). "Possible therapeutic targets for meningiomas include NF2, mTOR, PIK3CA, PDGFR, AKT, somatostatin receptor (SSTR), smoothened (SMO), cyclin-dependent kinases and inhibitors (CDKN2A/B, CDK4, CDK6), progesterone receptor and oestrogen receptor and VEGF/VEGFR." (PMID 40046333, 2025). "NF2-mutant meningiomas represent a cancer type where FAK inhibition shows actual therapeutic promise." (PMID 41487565, 2025).
meningioma (continued). "By the late 1990s and early 2000s, advances in genetic technology revealed additional genetic subtypes in NF2 wild-type meningiomas." (PMID 40936721, 2025). "Potential molecular mechanisms of MT include chromosomal abnormalities (Chromosome 22q deletion, NF2 gene mutation, loss of chromosome 1p), genomic alterations (FOXM1, CDKN2A/B and TERTp), and meningioma cancer stem cells." (PMID 39991581, 2025). "FAP expression was more frequent in meningiomas of CNS WHO grade 3 (vs. CNS WHO 2; p < 0.001), and samples with NF2 mutations (p = 0.032) or CDKN2A/B deletions (p = 0.013) compared to wildtype." (PMID 39969538, 2025). "Separate clustering of NF2- and TRAF7-mutated meningiomas has recently been documented in a large patient cohort." (PMID 41154381, 2025). "The Alliance A071401 trial represents a key inflection point in the translation of FAK inhibition for NF2-mutant meningiomas." (PMID 41487565, 2025). "Key genetic drivers, including mutations in NF2, SMO, KLF4, TRAF7, and chromosomal aberrations, allow for the stratification of meningiomas into distinct molecular subtypes, each associated with unique clinical outcomes and therapeutic vulnerabilities." (PMID 39941893, 2025). "While monotherapy with FAK inhibitors has shown promising disease control in NF2-mutant meningiomas, rational combination strategies are increasingly pursued to enhance efficacy and overcome resistance." (PMID 41487565, 2025). "We identified different histopathological subtypes within NF2 clusters, with NF2-cluster 2 predominantly exhibiting the psammomatous subtype of meningioma." (PMID 40562609, 2025). "In NF2-null meningioma cell lines, kinome profiling revealed activation of Eph receptor tyrosine kinases (EphA2, EphB1), c-KIT, and the Src/SFK pathway, targets of the FDA-approved kinase inhibitor Dasatinib." (PMID 41200151, 2025). "The aim of this study was to address similarities and differences between meningioma and VS to aid with therapeutic repurposing for NF2-SWN patients who have synchronous tumour burden." (PMID 41437121, 2025). "Nevertheless, approximately half of meningioma patients express NF2, indicating that meningioma occurrence is the result of multiple etiological factors." (PMID 39894505, 2025). "In meningioma cells, calcium signaling was also recently found to contribute to apoptosis induced by NF2, a well-known tumor suppressor in meningiomas." (PMID 41154381, 2025). "TRAF7 has previously been identified in NF2-independent meningiomas, malignant mesothelioma, and in small numbers of clear cell, papillary, and chromophobe RCCs." (PMID 40510153, 2025). "We analysed 109 CNS WHO Grade I meningiomas, comparing the Merlin immunostaining patterns with NF2 gene status." (PMID 40815185, 2025). "We revealed specific signatures in lower-grade meningioma such as NF2, AKT1E17K, and KLF4K409Q, and identified co-occurring mutations such as ATM-BIVM-ERCC5, PIK3C2B-SDHD, and ERCC4-MET." (PMID 40562609, 2025). "There was information regarding NF2 status in 70 graded pediatric meningiomas, and 2 (2.9%) patients had seizures as initial presenting symptoms." (PMID 40637916, 2025). "In this study, we showed that loss of Merlin immunostaining provided a high concordance with NF2 alteration in Grade I meningioma (sensitivity: 90.2%, specificity: 91.4%, positive predictive value: 90.2%, negative predictive value: 91.4%)." (PMID 40815185, 2025). "Convexity meningiomas are more commonly CNS WHO grades 2 and 3, consist of fibroblastic and transitional phenotypes, and are more frequently NF2-mutated." (PMID 40423252, 2025). "More specifically, aggressive meningiomas with allelic losses of NF2 show higher levels of several EMT-relevant proteins." (PMID 39796693, 2024). "Nearly a quarter of all meningiomas are characterized by TRAF7 loss, which is mutually exclusive with NF2 mutation." (PMID 39796693, 2024).